LRRC66 (leucine rich repeat containing 66)
Tractability: Antibody: UniProt predicts a signal peptide or a membrane-spanning region.
Gene: Protein-coding gene on chromosome 4 (51,993,614 to 52,020,363, reverse strand). Ensembl gene ENSG00000188993.
Subcellular location: Membrane
Gene Ontology:
Cellular component: membrane
Genetic constraint (gnomAD): Loss-of-function variants: 29 observed, 26.3 expected, observed/expected ratio (o/e) 1.1, 90% interval 0.82 to 1.5. The upper end of that interval is the gene's LOEUF score, 1.5, which puts it in group 6 of 6, group 1 being the genes least tolerant of losing a copy. Missense variants: 1,124 observed, 1,118.9 expected, observed/expected ratio (o/e) 1, 90% interval 0.96 to 1.05. Synonymous variants: 411 observed, 424.39 expected, observed/expected ratio (o/e) 0.97, 90% interval 0.89 to 1.05.
Homologues: Orthologues: chimpanzee LRRC66 (99% identical), macaque LRRC66 (83% identical), rabbit LRRC66 (53% identical), mouse Lrrc66 (47% identical), dog LRRC66 (46% identical), rat Lrrc66 (45% identical). Paralogues in human: FLRT1 (12% identical), FLRT3 (12% identical), FLRT2 (11% identical), LRRC4C (11% identical), LRRC4 (11% identical), LRRC4B (11% identical), RTN4R (10% identical), LRRTM4 (10% identical), RTN4RL1 (10% identical), LRRTM3 (10% identical), GP1BA (9% identical), PODN (9% identical), and 10 more.
Diseases named in the same sentence as LRRC66 in open-access papers:
LRRC66 is named in the same sentence as 1 disease in open-access papers, as found by Europe PMC text mining. Sharing a sentence is not in itself a finding about the gene and the disease. The quoted sentences say what the papers report.
type 2 diabetes (1 paper, 2020). "Although the roles of Serpina11, Cdh16, Lrrc27, and Lrrc66 in regulating islet function remain unclear, Acod1 is known to be important in modulating the immune system and mitochondrial function, and Fgf21 can protect against type 2 diabetes in mice by increasing insulin expression and secretion." (PMID 32527043, 2020).